Y_RNA (Y RNA )
Gene: Miscellaneous RNA gene on chromosome 3 (93,967,926 to 93,968,020, forward strand). Ensembl gene ENSG00000201339.
Homologues: Orthologues: chimpanzee Y_RNA (100% identical). Paralogues in human: RNY4P7 (87% identical), RNY4 (83% identical), RNY4P10 (83% identical), RNY4P19 (83% identical), Y_RNA (83% identical), RNY4P14 (82% identical), RNY4P24 (82% identical), RNY4P36 (82% identical), RNY4P6 (82% identical), Y_RNA (82% identical), RNY4P13 (81% identical), RNY4P37 (81% identical), and 92 more.